TLR7 (toll like receptor 7)
Diseases named in the same sentence as TLR7 in open-access papers (continued):
Sharing a sentence is not in itself a finding about the gene and the disease.
acute myeloid leukemia (5 papers, 2015 to 2025). Acute myeloid leukemia (AML) is a group of neoplasms arising from precursor cells committed to the myeloid cell-line differentiation. "Another study about developing a dendritic cell vaccine to be used for therapy of minimal residual disease in acute myeloid leukemia assessed the uptake of apoptotic leukemic cells by monocyte-derived DC (MoDC) and DC after stimulating the TLR7/8 receptor." (PMID 36851155, 2023). "In other hematological cancers, such as acute myeloid leukemia (AML), the mRNA expression levels of TLR2 and TLR4, but not of TLR9, were increased, contrary to what was observed in ALL, and expression of TLR7 and 9 was decreased in chronic myeloid leukemia (CML)." (PMID 34567117, 2021).
breast tumor (5 papers, 2016 to 2021). "Nevertheless, few investigations have been performed on the drug interactions between TKIs and TLR7 agonists administered simultaneously to treat breast tumor, which was our focus in this study." (PMID 28000738, 2016). "breast tumor myeloid cells, the expression of 5 TLR genes (TLR1, TLR2, TLR4, TLR7 and TLR8) were detected in >10% of cells and at moderate to high expression levels." (PMID 34956864, 2021). "Previous studies indicated that as early as the localized primary breast tumor stage, the NK presented a strong drop in IFN-γ production in response to either Type-I IFN or TLR7/8 ligand." (PMID 28977824, 2017). "Transcriptional analysis showed preferential expression of TLR8 and TLR7 in the LNR-cDC and –pDC subsets respectively (as opposed to migratory DC), both in HLN and BrC SLN, which were the exact DC subsets we identified as affected in the breast tumor-draining SLN." (PMID 31118093, 2019).
cervical cancer (5 papers, 2012 to 2024). A primary or metastatic malignant neoplasm involving the cervix. "Similarly, the use of LPS-derivative MPL for TLR4 stimulation and TLR7 agonist imiquimod has been restricted to vaccine formulations against HPV-associated cervical cancers and to topical treatments for basal-cell skin carcinomas, respectively." (PMID 26177198, 2015). "Recent investigation in mouse models has shown that imidazoquinoline therapy increases the number and activity of Treg cells in part through Treg expression of TLR7; however, opposite findings are reported in cervical cancer patients." (PMID 22481916, 2012). "When evaluating the gene expression patterns of TLR transcripts, specifically TLR1, TLR3, TLR4, TLR6, TLR7, TLR8 and TLR10, in HPV+ and HPV- cervical cancer tissue samples, we observed an increase in TLR4 expression and a decrease in TLR1 and TLR3 expression." (PMID 39208235, 2024). "In our study, the expression levels of TLR3, TLR4, TLR7, TLR8, NF-κB p65, and iNOS mRNA in the cervical squamous epithelial cells were significantly higher in the cervical cancer group than in the HR-HPV patients and healthy controls." (PMID 28626766, 2017). "In our study, upregulation of TLR4 in cervical cancer was the most significant among the TLRs examined (including TLR3, TLR4, TLR7, and TLR8)." (PMID 28626766, 2017). "We tested the TLR3, TLR4, TLR7, TLR8, NF-κB p65, and iNOS mRNA expression levels in the cervical tissue epithelial cells of the three groups and found that all mRNA levels were higher in the cervical cancer group than in the HR-HPV group and control group (P < 0.05)." (PMID 28626766, 2017). "However, the specific roles of TLR7 and TLR8 in cervical cancer are yet to be elucidated." (PMID 28626766, 2017).
depression (5 papers, 2020 to 2025). "We discovered that the conditioned media from WT, but not TLR7 KO, macrophages treated with miR-146a induced CM depression." (PMID 32958516, 2020).
encephalitis (5 papers, 2014 to 2025). An acute inflammatory process affecting the brain parenchyma. "Mice with single deficiencies of TLR7, TLR9, or TLR13 showed unaltered ability to control lung infection but were moderately more susceptible to encephalitis, in association with a decreased ability of microglia to mount cytokine responses in vitro." (PMID 32209688, 2020). "Using this model, mice with single deletions in specific TLRs, such as TLR2, TLR7, TLR9, or TLR13 were fully capable of controlling bacterial replication in the lung, but 30 to 45% of them developed encephalitis late during infection." (PMID 32209688, 2020). "Furthermore, as would be expected during viral encephalitis, IMQ, the active component of Aldara, stimulates TLR7 to mimic a viral response." (PMID 27160148, 2016). "The ablation of TLR2, TLR7, and TLR9 molecules did not significantly affect the progression of encephalitis caused by JEV." (PMID 25188232, 2014).
endometritis (5 papers, 2023 to 2025). An acute or chronic, usually bacterial infectious process affecting the endometrium. "Compared to resistant cows, endometritis-affected cows produced considerably more of the genes TLR4, LITAF, TNF-α, TKT, RPIA, TLR7, TNF-α, TKT, and AMPD1." (PMID 39195794, 2024). "When compared to resistant cows, endometritis-affected cows had considerably higher levels of the genes TLR4, TLR7, TNF, NCF4, and LITAF expression." (PMID 37756095, 2023). "Gene expression levels were considerably higher in endometritis-affected cows than in resistant ones for the genes TLR4, TLR7, TNF-α, NCF4, LITAF, OXSR1, TKT, RPIA, and AMPD1." (PMID 37368756, 2023). "Using PCR-DNA sequencing for the immunological (TLR4, IL10, TLR7, NCF4, TNF-α, and LITAF) genes, there were changes in the nucleotide sequence between endometritis-affected cows and healthy ones." (PMID 37756095, 2023). "The expression levels of the genes TLR4, TLR7, TNF-α, NCF4, LITAF, OXSR1, TKT, RPIA, and AMPD1 were significantly greater in endometritis-affected Holstein dairy cows than in resistant ones." (PMID 37368756, 2023). "Nucleotide sequence variations between healthy and endometritis-affected cows were revealed using PCR-DNA sequencing for immune (TLR4, TLR7, TNF-α, IL10, NCF4, and LITAF), antioxidant (ATOX1, GST, and OXSR1), and erythritol-related (TKT, RPIA, and AMPD1) genes were reported by44." (PMID 38459095, 2024). "Molecular genetic analyses of the immunological (TLR4, TLR7, TNF-α, IL10, NCF4, and LITAF), antioxidant (ATOX1, GST, and OXSR1), and erythritol-related (TKT, RPIA, and AMPD1) genes comparing healthy and endometritis cows found differences in nucleotide sequence and transcript levels." (PMID 37368756, 2023). "Single nucleotide variants (SNPs) in the genes were discovered using PCR-DNA sequencing for immune (TLR4, TLR7, TNF-α, IL10, NCF4, and LITAF), antioxidant (ATOX1, GST, and OXSR1), and erythritol-related (TKT, RPIA, and AMPD1) genes found in resistant and endometritis-infected Holstein dairy cows." (PMID 37368756, 2023). "The immune (TLR4, TLR7, TNF-α, IL10, NCF4, and LITAF), antioxidant (ATOX1, GST, and OXSR1), and erythritol-related (TKT, RPIA, and AMPD1) genes in endometritis-affected and healthy Holstein dairy cows were characterized in this research using a PCR-DNA sequencing technique." (PMID 37368756, 2023). "Nucleotide sequence variations between healthy and endometritis-affected cows were revealed using PCR-DNA sequencing for immune (TLR4, TLR7, TNF-α, IL10, NCF4, and LITAF), antioxidant (ATOX1, GST, and OXSR1), and erythritol-related (TKT, RPIA, and AMPD1) genes." (PMID 37368756, 2023).
HCMV infection (5 papers, 2011 to 2021). "The objective of the current study is to determine the frequencies of SNPs in the TLR3 (rs3775290, rs3775291, rs3775296) and TLR7 (rs179008, and rs5741880) genes and investigate the associations between these polymorphisms and HCMV infection in children." (PMID 28046022, 2017). "It is interesting that responses to the TLR7/8 ligand CLO75 are particularly affected by co-existing HCMV infection in our study." (PMID 32707906, 2020). "The inhibited cytokine expression, observed after treatment of pDCs with CpG, agonists for TLR7 and TLR9, suggested an involvement of the reported TLRs in the development of HCMV infection." (PMID 28340580, 2017). "We genotyped 59 children with symptomatic HCMV infection and 78 healthy individuals for SNPs in the TLR3 (rs3775290, c.1377C>T, F459F; rs3775291, c.1234C>T, L412F; rs3775296, c.-7C>A) and TLR7 (rs179008, c.32A>T, Q11L; rs5741880, c.3+1716G>T) genes." (PMID 28046022, 2017). "Multiple-SNP analysis showed that the most common haplotype for the TLR3 SNPs rs3775290, rs3775291, rs3775296 and the TLR7 SNPs rs179008 and rs5741880 was CCCAT (21.5% for uninfected cases) and CTCAG (20.6% for children with HCMV infection)." (PMID 28046022, 2017). "Such overlapping effects between TLR7 and TLR9 have been observed during murine cytomegalovirus infection." (PMID 21253574, 2011). "Therefore, our results suggest that HCMV infection suppresses innate reactivity to TLR2 and TLR7/8 stimulation in infant females but not in males." (PMID 32707906, 2020).
liposarcoma (5 papers, 2019 to 2022). A usually painless malignant tumor that arises from adipose tissue. "In liposarcoma, exosomal miR-25-3p and miR-92a-3p produced by liposarcoma cells could induce tumor-associated macrophages to secrete IL6 via TLR7/8-dependent pathway, thereby enhancing the proliferation and invasion of liposarcoma cells." (PMID 34692482, 2021). "Some studies showed that TLR7 interacts with miR-25-3p, thereby stimulating the secretion of IL6 by macrophages and promoting the growth and spread of liposarcoma." (PMID 34026613, 2021).
liver cirrhosis (5 papers, 2016 to 2020). "The role of TLR7 in NASH/NAFLD, liver fibrosis, or liver cirrhosis has been widely overlooked in the clinical setting; however, recent studies suggest that ALD-mediated inflammation and fibrosis is linked to hepatic TLR7 overexpression." (PMID 31717860, 2019). "The importance of TLR7 up-regulation in individuals who have progressed to the liver cirrhosis stage and unresponsiveness to IFN has been discussed before." (PMID 29379591, 2017).
liver fibrosis (5 papers, 2016 to 2024). "Exosomes can also deliver specific miRNAs from infected hepatocytes to hepatic stellate cells (HSC), where these miRNAs trigger several pathways associated with liver fibrosis, including TGB-β signaling and the TLR7, and B-cell activation pathways." (PMID 38396820, 2024). "In contrast, TLR7 has been identified as a protective factor in hepatic fibrosis development in both CCL4 and BDL murine fibrosis models." (PMID 31717860, 2019). "In addition, TLR9 expressed on HSCs can also be activated by DNA fragments released from hepatocytes, which aggravates the progression of liver fibrosis, while TLR3 and TLR7 signaling could impede liver fibrosis progression." (PMID 35990625, 2022). "The elevated levels of TLR7 in early stage of fibrosis is evidence for the implication of TLR7 in the immune response against HCV infection whereas the inversion of the expression pattern in advanced fibrosis patients suggests a protective role of TLR7 against liver fibrosis." (PMID 27135246, 2016). "In conclusion, TLR7 and MyD88 are possible candidates as biomarkers for the progression of HCV-induced liver fibrosis and/ or targets for therapeutic intervention to halt worsening of the clinical course of HCV chronic infection in patients who are uneligible or resistant to DAAs treatment." (PMID 27135246, 2016).
lupus erythematosus (5 papers, 2018 to 2022). An autoimmune, connective tissue chronic inflammatory disorder affecting the skin, joints, kidneys, lungs, heart, and the peripheral blood cells. "Interestingly, the TLR9 signaling limits the TLR7-mediated immune responses to ssRNA and CpG DNA self-antigens in B-cells in lupus erythematosus patients." (PMID 35955609, 2022).
lymph node metastasis (5 papers, 2019 to 2025). "In lymph node metastasis, high TLR7 intensity was associated with significantly worse DSS compared to low intensity (26.4% vs. 84.9%, p = 0.028)." (PMID 38709790, 2024). "For lymph node metastases, high cytoplasmic TLR7 intensity associated with worse DSS compared to low cytoplasmic intensity (26.4% vs. 84.9%, p = 0.028)." (PMID 38709790, 2024). "High TLR7 intensity in lymph node metastases associated with worse survival both in univariate model and after adjusting for confounders." (PMID 38709790, 2024). "High TLR7 expression in lymph node metastases associates with worse disease specific survival." (PMID 38709790, 2024). "Adjusted HR in high cytoplasmic TLR7 lymph node metastasis intensity group was 3.90 (95% CI 1.07–14.3) when compared to low intensity." (PMID 38709790, 2024). "A larger proportion of patients with high cytoplasmic TLR7 intensity in lymph node metastases tended to have high T-class (T3-4) compared to the low intensity group (p = 0.049)." (PMID 38709790, 2024). "In this study, we utilized the R package rms to integrate data on seven gender-related characteristics, including stage grading, T stage, lymph node metastasis, distant metastasis, smoking status, and TLR7 gene expression level, as well as survival time and survival status." (PMID 39857735, 2025). "Of the 95 lymph node metastases, analyzable samples were available for 70 (TLR1), 72 (TLR2), 77 (TLR4), 58 (TLR5), 76 (TLR6), 72 (TLR7), 76 (TLR8) and 70 (TLR9) cases." (PMID 38709790, 2024). "In the present study, TLR7, recognizing intrinsic ligands, seemed to be prognostic in lymph node metastases, which are also not in direct contact of the bowel lumen." (PMID 38709790, 2024). "Moreover, a high TLR7 expression indicated a better prognosis amongst patients with stage III disease (HR 0.60; 95% CI 0.38–0.95; p = 0.029), amongst those with a pT4 tumour (HR 0.51; 95% CI 0.32–0.80, p = 0.003), and amongst those with lymph-node metastasis (HR 0.67; 95% CI 0.47–0.96; p = 0.029)." (PMID 31467388, 2019).
metabolic syndrome (5 papers, 2019 to 2025). A cluster of metabolic risk factors for CARDIOVASCULAR DISEASES and TYPE 2 DIABETES MELLITUS. "Thus, in the current study we evaluated the impact of high fat diet (HFD) on the development of SLE and metabolic syndrome in TLR8-deficient mice (TLR8ko) that spontaneously develop SLE due to increased TLR7 signaling by DCs." (PMID 31552019, 2019). "TLR7 may be the connection between metabolic syndrome and SLE because of the elevated risk of metabolic syndrome in SLE patients and its association with the onset of SLE." (PMID 40976999, 2025). "Evidence is also accumulating to suggest that TLR7 may play a role in several features of the metabolic syndrome (MetS)." (PMID 38346802, 2024). "Given the increased risk of metabolic syndrome in SLE patients and the fact that TLR7 is implicated in SLE development we hypothesized that TLR7 might be the connecting link between metabolic syndrome and SLE." (PMID 31552019, 2019). "Here, we report the implication of TLR7 signaling in high fat diet (HFD)-induced metabolic syndrome and exacerbation of lupus autoimmunity in TLR8-deficient (TLR8ko) mice, which develop spontaneous lupus-like disease due to increased TLR7 signaling by dendritic cells (DCs)." (PMID 31552019, 2019). "There has never been any information published on the role that TLR7 plays in the long‐term inflammation of SLE in relation to obesity or metabolic syndrome." (PMID 40976999, 2025).
neuroblastoma (5 papers, 2018 to 2025). Neuroblastoma (NB) is the most common solid, extracranial childhood tumor. "In response to PGE2 stimulation, this miRNA is specifically sorted into sEV and exerts a paracrine function in the TME of neuroblastoma by modulating fibroblast differentiation via TLR7/8 binding." (PMID 37731742, 2023). "Given the important role of sEV in NB progression, the role of sEV-miR-574-5p as a TLR7/8 ligand in neuroblastoma is of particular interest because of its impact on fibroblast differentiation." (PMID 37731742, 2023). "A new research team found that resiquimod enhances immunological response in human neuroblastoma cell cultures via TLR7-NFκB-C-C motif chemokine ligand 2 signaling, providing a novel possible therapy approach for neurotropism due to viruses." (PMID 40673003, 2025). "Therefore, we decided to further investigate the role of miR-574-5p in the neuroblastoma microenvironment in terms of its intracellular function as a regulator of PGE2 biosynthesis and its extracellular function as a TLR7/8 ligand." (PMID 37731742, 2023). "It was previously demonstrated that RSV could infect microglia and Neuro-2a (N2a) mouse neuroblastoma cells in vitro, and the expression of Toll-like receptor 3 (TLR3)/Toll-like receptor 7 (TLR7) in RSV-infected N2a cells was time-dependent." (PMID 33953861, 2021).
adult-onset Still disease (4 papers, 2013 to 2025). A rare inflammatory multisystem disorder characterized clinically by fever of unknown origin, arthralgia or arthritis, hyperleucocytosis, and typical skin rash. "The objective of this study was to investigate the potential role of the Toll-like receptor 7 (TLR7) signaling pathway in the pathogenesis of adult-onset Still's disease (AOSD)." (PMID 23497717, 2013). "This study investigated the role of Toll-like receptor 1 (TLR1), TLR2, TLR4, TLR7, and TLR9 in patients with adult-onset Still’s disease (AOSD)." (PMID 35715478, 2022).
airway hyperresponsiveness (4 papers, 2018 to 2025). "On the other hand, in males, the intensified Th1 response could suppress Th2-driven disease, potentially increasing their risk of airway hyperresponsiveness if TLR7 activity is reduced." (PMID 40143355, 2025). "Stimulating TLR7 has been proposed as a treatment for airway hyperresponsiveness (AHR) induced by allergic airway inflammation, a finding supported by studies in both rats and mice." (PMID 39614276, 2024). "TLR7/8 agonists 3M-052, with either antigen (Lipo-OVA) or viral envelope proteins (Viro), showed a compensatory effect in resolving airway hyperresponsiveness." (PMID 40951841, 2025).
bladder cancer (4 papers, 2015 to 2024). "Recently, imiquimod and TMX-202 (TLR7 agonists) were tested for bladder cancer immunotherapy, while CpG ODN (a TLR9 agonist) and HP-NAP (a TLR2 agonist) demonstrated reduced tumor growth in an MB49 bladder cancer mouse model." (PMID 38542078, 2024). "Apart from the TLR-7 agonists discussed here, recent and ongoing clinical trials reporting on immunotherapy for bladder cancer predominantly assess systemic checkpoint inhibitors (for example PD-L1, PD-1 and CTL-A4) targeting advanced and metastatic disease." (PMID 29767328, 2018). "This experiment turned out to be underpowered but in this aggressive bladder cancer model, a lower number of tumor-positive rats after treatment with TLR-7 agonists indicate a promising potential for the treatment of non-muscle invasive bladder cancer." (PMID 29767328, 2018). "In this in vivo experiment, we tested the TLR-7 agonists TMX-101 and TMX-202 in an orthotopic bladder cancer rat model." (PMID 29767328, 2018). "Previously, these BCG-derived products (BCG-CWS or BCG-derived DNA/RNA) were found to induce apoptosis in bladder cancer cells by activating TLR2, TLR4, TLR7, and TLR9 and thus inducing the myeloid differentiation primary response gene 88 (MYD88) pathway of extrinsic apoptosis." (PMID 36248858, 2022). "In this aggressive bladder cancer model, a lower number of tumor-positive rats after treatment with TLR-7 agonists indicates activity for the treatment of non-muscle invasive bladder cancer." (PMID 29767328, 2018).
chronic hepatitis C (4 papers, 2009 to 2020). "TLR7 IVS2-151G/A allele was associated with the protection of female patients of chronic hepatitis C (P ≤ 0.001, OR =0.46)." (PMID 32565728, 2020). "Similarly, TLR7 rs179009, IVS2-151A/G polymorphism was associated with spontaneous clearance of HCV in female patients and chronic hepatitis C." (PMID 32565728, 2020).